BRD4 (bromodomain containing 4)
Diseases named in the same sentence as BRD4 in open-access papers (continued):
Sharing a sentence is not in itself a finding about the gene and the disease.
tumor (continued). "Recently, a study reported that BRD4 functions with E2F1 to regulate cell cycle associated programs and that BRD4 inhibitors decrease growth of tumor models." (PMID 40370549, 2025). "Together, our study revealed that BRD4 plays a fundamental role in direct activation of tumor LP programs and that its inhibitor AZD5153 is highly promising in effective treatment of the lethal forms of the diseases." (PMID 40370549, 2025). "BET inhibitors have shown promise in clinical trials; BET inhibitors act by competitively inhibiting BRD4 function, thereby suppressing tumor growth." (PMID 41194824, 2025). "For EGFR-driven NSCLC, nanocarrier-assisted PROTAC delivery significantly enhanced in vivo antitumor efficacy in resistant xenografts, while co-delivery of EGFR and BRD4 degraders in a single nanoplatform achieved synergistic tumor suppression." (PMID 41008623, 2025). "For instance, the study demonstrated that co-inhibition of TOP1 and bromodomain-containing protein 4 (BRD4) synergistically induces tumor regression." (PMID 41155268, 2025). "This study reveals a new way through which BET inhibitors suppresses tumor cell growth and provides a rationale for targeting BRD4 and UFMylation to enhance ferroptosis in solid tumors." (PMID 41249136, 2025). "Loss of BRD4 in the myeloid compartment led to significantly decreased levels of MDSCs in tumor-bearing mice, suggesting an important role for BRD4 in MDSC expansion and survival." (PMID 40762981, 2025). "The UMSNs@phoBET1 nanocage represents a breakthrough in precision PROTAC delivery by utilizing upconversion nanoparticles (UCNPs) to convert 980 nm NIR light into localized UV activation, enabling deep-tissue BRD4 degradation with >80% tumor inhibition." (PMID 40871058, 2025). "In xenograft tumor models, the self-assembledtrivalent BRD4 degraderdemonstrated significant antitumor efficacy (tumor growth inhibition,TGI > 60%) without inducing body weight loss or hepatorenal toxicity." (PMID 41311923, 2025). "The system demonstrated potent tumor accumulation and excellent biosafety, achieving complete BRD4 degradation with concomitant caspase-3 activation." (PMID 40871058, 2025). "This degradation of BRD4 protein increased the tumor’s sensitivity to radiation, resulting in a synergistic enhancement of antitumor effects both in vitro and in vivo." (PMID 41012497, 2025). "Long - term treatment with JQ1 or the destabilization of LSD1 induced by PELI1 will cause the BRD4/LSD1/NuRD complex to become ineffective, thereby leading to tumor resistance to JQ1 and broad - spectrum therapeutic compounds." (PMID 39838405, 2025). "Degradation of BRD4 protein and generation of ROS further triggered apoptotic pathways, synergistically enhancing apoptosis in tumor cells." (PMID 41049731, 2025). "As previously seen, the administration of PLX51107 in combination with anti–PD-L1 in LLC tumor–bearing BRD4 WT mice led to a significant reduction in tumor volumes compared with anti–PD-L1 therapy alone (P < 0.0001)." (PMID 40762981, 2025). "When exposed to X-ray radiation, the diselenide bonds were broken, releasing MZ1 specifically at the tumor site to degrade BRD4 proteins." (PMID 40284496, 2025). "In a colorectal cancer model, PROTAC-mediated degradation of BET proteins (BRD2, BRD3, and BRD4) in tumor cells induces immunogenic cell death and activates DR5-mediated apoptosis." (PMID 41583469, 2025). "Splenic MDSCs were isolated from LLC tumor–bearing BRD4 cKO mice and littermate controls (WT) to confirm reduced expression of BRD4 by immunoblot." (PMID 40762981, 2025). "For example, different isoforms of BRD4 explain why earlier studies reported the BRD4 reader protein as a tumour suppressor, while others described it as an oncogene." (PMID 41168462, 2025).
tumor (continued). "BRD4 has been identified as a potential therapeutic target for tumors owing to its contribution to tumor pathogenesis." (PMID 38768083, 2024). "In vivo antitumor study suggested that combining PDT and BRD4 degradation resulted in highly efficient induction of tumor cell apoptosis and inhibition of tumor growth." (PMID 38773495, 2024). "We further detected the Wnt and NF-κB2 signaling pathways to elucidate the tumour-promoting mechanism of the AL139294.1–miR-204-5p–BRD4 axis in NSCLC." (PMID 38229152, 2024). "This underscores BRD4’s pervasive and substantial involvement in the biological processes of tumor cells, including GBM." (PMID 38365636, 2024). "In the mouse xenograft model, significant changes in tumor growth, volume, weight, and BRD4-related gene expression were observed, suggesting the antitumor effects of BRD4 inhibitors." (PMID 38473320, 2024). "On clinical specimens, we found that mature DCs infiltrating tumor tissues of TNBC patients were negatively correlated with the expression of BRD4, which was consistent with the result in animal model." (PMID 38811964, 2024). "Western blotting showed that overexpression of AL139294.1 in EVs derived from NCI-H1299 cells elevated the protein expression of BRD4 in tumour tissues." (PMID 38229152, 2024). "Altogether, these results further supported the role of SMAD3 in controlling tumor recognition by NK cells through active cooperation with the epigenetic reader BRD4 in regulating inhibitory receptors and NK exhaustion genes." (PMID 38519469, 2024). "In vivo experiments demonstrated that NGP-57 effectively degraded BRD4 protein within tumor tissues and exhibited potent inhibition against MDA-MB231 tumor growth models." (PMID 38773495, 2024). "Previous studies have found that inhibiting BRD4 can induce cell cycle arrest and trigger apoptosis in tumor cells." (PMID 38365636, 2024). "To investigate the effects of endothelial Brd4 deletion on developmental neural stem cells and potential tumour invasion, we conducted experiments using Brd4cKO(by breeding Brd4 flox mice with Tie2 cre mice) mice." (PMID 39010274, 2024). "NGP-42 has an important function in specifically targeting the HER2/neu receptor on tumor cells and selectively degrading BRD4 in those cells, particularly in the BT-474 and SK-BR-3 cell lines." (PMID 38773495, 2024). "Through an examination of the CCLE database, we have ascertained that the average Chronos dependency score for BRD4 in diverse tumor cell lines hovers around -1." (PMID 38365636, 2024). "In the CPTAC cohort, the protein expression pattern of BRD4 was similar to its mRNA expression pattern in LUAD tissues and was positively associated with earlier tumour stages I and II." (PMID 38229152, 2024). "In conclusion, our study demonstrated that MZ1 showed significant anti-tumor effects both in vitro and in vivo by selectively inhibiting BRD4 and SE-regulated oncogenes." (PMID 38365636, 2024). "At the gene expression level, fusion calling from RNA-sequencing data of six tumor samples again demonstrated Brd4::Nutm1 fusion with the designed junction as the only recurrent fusion." (PMID 38724194, 2024). "To investigate the potential roles of BRD4 in tumors, we initially assessed the expression of BRD4 in diverse tumor cell lines through the CCLE database." (PMID 38365636, 2024). "In this study, we find that CNS embryonal tumor with BRD4::LEUTX fusion is a provisional tumor type occurring in young children." (PMID 38500181, 2024). "One case presented a dedicated case report for a tumor matching to the methylation class “CNS embryonal tumor with BRD4::LEUTX fusion”, with demonstration of the fusion." (PMID 38500181, 2024). "In this context, we rationally engineered a novel PROTAC formulation (ARV-825-loaded microbubbles [ARV-MBs]) for the tumor-targeted degradation of the BET protein BRD4 in TNBC." (PMID 39140036, 2024).
tumor (continued). "We demonstrate that CNS embryonal tumor with BRD4::LEUTX fusion comprises a well-defined methylation class/cluster." (PMID 38500181, 2024). "From these findings, we conclude that the specific inhibition of BRD4-dependent transcription is beneficial for viral propagation and anti-tumour efficacy and is a promising avenue for future clinical translation." (PMID 38279262, 2024). "Targeted inhibition of BRD4 suppresses tumour growth in breast and prostate cancer, as well as in acute myeloid leukaemia and diffuse large B-cell lymphoma." (PMID 38191874, 2024). "Pharmacological targeting with SR8278 diminishes the function of both REV-ERBα and FOXA1 and synergizes with BRD4 inhibitor in effective suppression of tumorigenic programs and tumor growth." (PMID 39383000, 2024). "Collectively, these data indicated that the aberrant expression of BRD4 played a role in tumor initiation and was correlated with a less favorable prognosis in GBM patients." (PMID 38365636, 2024). "More importantly, we found that the expression levels of Notch1 were positively correlated with BRD4 proteins in Western blot analysis and immunohistochemistry results of in vivo tumor samples." (PMID 39544152, 2024). "The findings revealed that BRD4 was consistently upregulated in tumor cell lines, with its expression levels notably elevated in GBM compared to the overall average." (PMID 38365636, 2024). "Gene expression was available for 3 of the 4 cases profiled at the NIH, where the expression of LEUTX and BRD4 was compared to the clinical dataset of > 2700 samples of a variety of tumor types with gene expression data available." (PMID 38500181, 2024). "JQ-1 is a typical BRD4 inhibitor with the ability to directly fight tumor cells and evoke antitumor immunity via reducing the expression of PD-L1." (PMID 38203835, 2024). "In terms of mechanism, MCM@UN blocked BRD4 and PD-L1 to prompt dying tumor cells to disintegrate and expose tumor antigens." (PMID 38811964, 2024). "This light-triggered release mechanism allowed for precise control over BRD4 degradation, a key target involved in tumor growth regulation." (PMID 38773495, 2024). "NUV-868 (NCT05252390) is a BRD4 inhibitor; BRD4 is a transcriptional coactivator of genes involved in tumor progression, angiogenesis, metastasis, and resistance to therapies." (PMID 38731844, 2024). "As a possible epigenetic therapeutic target, BRD4 inhibitors were presently undergoing preclinical and clinical trials for the treatment of various tumor types." (PMID 39323672, 2024). "Brd4 expresses highly in endothelial cells within various tumours and is positively correlated with numerous invasive genes, making it an ideal focal point for further research on the relationship between blood vessels and cell competition." (PMID 39010274, 2024). "It has been demonstrated that ARV-825, which combines a BRD4 inhibitor with a cereblon ligand using PROTAC technology, showed to be more effectively breaking down BRD4, inhibiting tumor growth effectively and consistently." (PMID 38130463, 2023). "Because we observed that the abscopal effects of local RT increased upon the addition of the BRD4 inhibitor, we profiled the immune cells in spleens and the tumor-draining lymph nodes to determine the effects of the treatments on systemic immunity." (PMID 37685868, 2023). "This study used bioinformatics analysis tools to screen tumor data from public databases for target gene analysis, and provided multiple layers of evidence for the potential of BRD4 as a molecular marker in GBM." (PMID 36711038, 2023). "Next, in follow up period after cessation of chemotherapy, we observed profound differences in tumor recurrence status between BRD4-high and BRD4-low PDX modes." (PMID 37705995, 2023). "Collectively, these results demonstrate that treatment with ARV@PDSA not only substantially inhibited tumor growth by inhibiting BRD4 and c‐Myc but also showed a superior anti‐tumor therapy strategy than free PROTACs." (PMID 37066758, 2023).
tumor (continued). "Inhibition of BRD4 can inhibit the proliferation of glioma cells and promote the apoptosis of tumor cells, and knockout of YAP/TAZ can prevent tumor formation in SCID mice injected with primary cancer cell lines in situ." (PMID 36875159, 2023). "Bromodomain-Containing Protein 4 (BRD4) can play an important role in gene transcriptional regulation of tumor development and survival by participating in histone modification epigenetic mechanism." (PMID 37446009, 2023). "It has been reported that a combination of TAF1 and BRD4 inhibitors offered synergistic anti-proliferative effects in tumor cells." (PMID 37142850, 2023). "Together, these in vitro results demonstrate that ARV@PDSA treatment not only facilitated the BRD4 degradation but also efficiently drugged the undruggable oncogene c‐Myc, again highlighting the promise of the Nano‐PROTACs strategy for anti‐tumor therapy." (PMID 37066758, 2023). "The YAP/TAZ/BRD4 complex participates in tumour progression, angiogenesis, metastasis and resistance to therapy." (PMID 37994501, 2023). "The expression of BRD4 was positively correlated with tumor purity, and negatively correlated with immune infiltration abundance of macrophage, neutrophil and CD8 + T-cell, respectively." (PMID 36711038, 2023). "Further in vivo data showed that the Ovcar4 cell line-based tumor model is highly resistant to cisplatin/paclitaxel treatment even prior overexpression of BRD4 isoforms, which is in agreement with literature." (PMID 37705995, 2023). "To further investigate the anti‐tumor mechanism of ARV@PDSA, we determined the expressions of BRD4 and c‐Myc in tumor samples harvested one day after the last treatment." (PMID 37066758, 2023). "We show that combining the TOP1 inhibitor irinotecan with the BRD4 inhibitor JQ1 synergistically kills the tumor cells in the PDX model of both tumor types." (PMID 37831776, 2023). "The expression of HIF-1α and PD-L1 in the tumor was significantly downregulated by the BRD4 inhibitor." (PMID 37685868, 2023). "Both local RT alone and combination therapy resulted in excellent survival rates for tumor-bearing mice; these rates were significantly better than the survival rates of the control and BRD4 inhibitor-alone mice." (PMID 37685868, 2023). "The Heidelberg DNA-methylation classifier classified this case as “CNS Embryonal Tumor with BRD4:LEUTX Fusion”." (PMID 36934287, 2023). "Sinonasal NC presents typical undifferentiated or poorly differentiated cells, abrupt keratinization features and heterogeneous genotypes, including BRD4::NUTM1 and BRD3::NUTM1 fusions, with low tumor mutation burden and stable microsatellites." (PMID 38239638, 2023). "Immunohistochemistry (IHC) staining assay showed similar results that the highest BRD4 and c‐Myc reduction of tumor tissue were observed after treatment with 10 mg kg−1 ARV‐771@PDSA." (PMID 37066758, 2023). "Transcriptional activators (such as BRD4 and CDK7) are highly enriched in oncogenic SE regions, and their inhibition preferentially affects SE-associated genes in tumor cells." (PMID 36720920, 2023). "The level of BRD4 expression was significantly correlated with the tumor immune microenvironment in GBM patients." (PMID 36711038, 2023). "In conclusion, sinonasal NC presents typical undifferentiated or poorly differentiated cells, abrupt keratinization features and heterogeneous genotypes, including BRD4::NUTM1 and BRD3::NUTM1 fusions, with low tumor mutation burden and stable microsatellites." (PMID 38239638, 2023). "Our findings indicate that HMJ-38 targets BRD4, CDK2, CHEK1/2, and EGFR, which have been implicated in the death of tumor cells and DNA damage pathways." (PMID 38532833, 2023). "These factors should be taken into consideration when evaluating clinical tumor samples for BRD4 abundance." (PMID 37705995, 2023).
tumor (continued). "The BRD2 and BRD4 up-regulation in the GBM models prompted us to better characterize the BET protein involvement in tumor progression, taking advantage of the well-characterized and specific pan-inhibitor JQ1." (PMID 37108181, 2023). "The study found that BRD4 protein was significantly higher expressed in tumor tissues than in normal tissues." (PMID 36711038, 2023). "Early studies have defined the tumor-protective function of BRD4 in breast cancer and Hutchinson-Gilford progeria syndrome." (PMID 37705995, 2023). "In our study, the combination treatment significantly delayed the growth of an unirradiated secondary tumor, compared to BRD4 inhibitor alone." (PMID 37685868, 2023). "We previously demonstrated that targeting two independent arms of promoter-proximal pausing regulation through inhibition of TOP1 and BRD4 synergistically inhibited tumor growth in vitro." (PMID 37831776, 2023). "BRD4 regulates the self-renewal ability of glioma-initiating cells by interaction in the Notch1 promoter region and involvement of tumor metabolism." (PMID 37924094, 2023). "These super-enhancers are characterized by BRD4 binding, and BRD4 knockdown or inhibition reduces diffuse intrinsic pontine glioma cell proliferation in vitro and tumor progression in mouse models." (PMID 38135679, 2023). "Despite distinct effects of the overexpression of individual BRD4 isoforms on cell proliferation and tumor growth, both isoforms contributed to chemotherapy resistance in our study." (PMID 37705995, 2023). "The antitumor function of 3',4',7,8-tetrahydroxyflavone (THF), a specific BRD4 inhibitor, was studied through in vivo tumor model and mouse studies, and the protein levels of c-Myc, PD-L1, and RelB were examined in tumor model under THF treatment." (PMID 37924094, 2023). "BRD4 is found to be phosphorylated leading to its stability and tumor-promoting transcriptional program." (PMID 37689115, 2023). "The combination of BRD4 inhibitor and RT significantly suppressed tumor growth compared to RT alone." (PMID 37685868, 2023). "Specifically, bioinformatic and immunohistochemistry analysis showed that BRD4 protein was more highly expressed in tumor tissues than that in normal tissues." (PMID 36711038, 2023). "This study also carried out immunofluorescence experiments to verify that BRD4 showed green fluorescence in tumor cells, indicating the high expression." (PMID 36711038, 2023). "Again, this observation matchedwith the essential role of oncogene phosphorylation to induce tumor progression; examples include the phosphorylation of BRD4, Smad3, and EGFR." (PMID 37106813, 2023). "To evaluate the significance of PD-L1 and BRD4 inhibitor on tumors, we used a mouse tumor model sensitive to PD-1 blockade." (PMID 37924094, 2023). "In contrast, BRD4-high model demonstrated a partial response to cisplatin/paclitaxel treatment, which was followed by a rapid tumor recurrence after therapy cessation." (PMID 37705995, 2023). "In contrast, PGD7 NPs remarkably suppressed BRD4 expression in vivo by ~80% in the tumour tissue due to the improved delivery efficacy of ARV771 from the POLY-PROTAC NPs." (PMID 35882867, 2022). "BRD4 is an important epigenetic factor and has been commonly used for drug development for tumor treatment." (PMID 35758684, 2022). "Our work demonstrates that administration of JQ1 (BRD4 inhibitor) successfully depleted c-Myc levels with a striking impact on tumor spread/metastasis with only minor inhibitory activity on the primary tumor." (PMID 36329064, 2022). "BRD4 inhibition is also known to promote anti-tumor immunity by suppressing Programmed death-ligand 1 (PD-L1) expression." (PMID 35226658, 2022). "Compared with the Ctrl or Ctrl+Sh-NC group, tumor tissues derived from the HG or HG + Sh-NC group exhibited increased positivity for Pin1, BRD4, NAP1L1, PCNA, and MMP9, and reduced positivity for P21." (PMID 35461311, 2022).